GRK7 (G protein-coupled receptor kinase 7)
Description:
Retina-specific kinase involved in the shutoff of the photoresponse and adaptation to changing light conditions via cone opsin phosphorylation, including rhodopsin (RHO).
Synonyms: GPRK7
Tractability: Small molecule: a high-quality ligand is known; it belongs to a druggable protein family. PROTAC: a small molecule that binds it is known.
Target class: AGC protein kinase GRK family; Kinase; AGC protein kinase group; AGC protein kinase GRK subfamily; Enzyme; Protein Kinase
Gene: Protein-coding gene on chromosome 3 (141,763,408 to 141,819,352, forward strand). Ensembl gene ENSG00000114124.
Subcellular location: Membrane
Subcellular location (Human Protein Atlas): Golgi apparatus
Pathways (Reactome):
Sensory Perception: Inactivation, recovery and regulation of the phototransduction cascade
Gene Ontology:
Molecular function: protein binding; rhodopsin kinase activity; ATP binding; G protein-coupled receptor kinase activity; protein kinase activity; protein serine/threonine kinase activity
Biological process: regulation of opsin-mediated signaling pathway; regulation of signal transduction; regulation of G protein-coupled receptor signaling pathway; signal transduction
Cellular component: cytoplasm; membrane; photoreceptor disc membrane
Genetic constraint (gnomAD): Loss-of-function variants: 23 observed, 38.96 expected, observed/expected ratio (o/e) 0.59, 90% interval 0.42 to 0.84. The upper end of that interval is the gene's LOEUF score, 0.84, which puts it in group 3 of 6, group 1 being the genes least tolerant of losing a copy. Missense variants: 644 observed, 735.29 expected, observed/expected ratio (o/e) 0.88, 90% interval 0.82 to 0.94. Synonymous variants: 256 observed, 294.03 expected, observed/expected ratio (o/e) 0.87, 90% interval 0.79 to 0.97.
Homologues: Orthologues: chimpanzee GRK7 (99% identical), macaque GRK7 (97% identical), rabbit GRK7 (86% identical), dog GRK7 (86% identical), pig GRK7 (85% identical), guinea pig GRK7 (81% identical), tropical clawed frog grk7 (69% identical), zebrafish grk7a (60% identical), zebrafish grk7b (58% identical). Paralogues in human: GRK1 (46% identical), GRK4 (45% identical), GRK6 (44% identical), GRK5 (44% identical), GRK3 (33% identical), GRK2 (32% identical), RSKR (16% identical).
Diseases named in the same sentence as GRK7 in open-access papers:
GRK7 is named in the same sentence as 5 diseases in open-access papers, as found by Europe PMC text mining. Sharing a sentence is not in itself a finding about the gene and the disease. The quoted sentences say what the papers report.
retinal degeneration (2 papers, 2023 to 2024). Degeneration of the retina. "Although there are several reports describing grk7-knockdown or -KO zebrafish, all of them focused on their impaired response recovery without long-term observation and did not investigate light-induced damage or retinal degeneration." (PMID 38646933, 2024).
Blindness (1 paper, 2013). Blindness is the condition of lacking visual perception defined as a profound reduction in visual perception. "For example, knockdown of the cone-specific opsin kinase GRK7 has a strong effect on photoresponse recovery and ectopic expression of GRK7 in zebrafish rods lowered the photosensitivity of rods; mutations in key proteins of the phototransduction cascade lead to blindness and cone degeneration." (PMID 23940527, 2013).
breast carcinoma (1 paper, 2022). "Moreover, a genome-wide association study (GWAS) of breast cancer declared identification of 65 novel loci associated remarkably with a high risk of breast cancer at P < 5 × 10− 8 such as FES, MAP 3 K11, CLK2, GRK7, USP25, DFFA, PKP1, and ZKSCAN3." (PMID 35650591, 2022).
cancer (1 paper, 2021). A tumor composed of atypical neoplastic, often pleomorphic cells that invade other tissues. "Briefly discussing the role of GRKs in cancer, GRK1 and GRK7 were shown to play a role in embryogenesis, while interacting indirectly with Rho GDP-dissociation inhibitor (RhoGDI) and phosphodiesterase γ (PDEγ), both of which are shown to be abnormally regulated in cancer." (PMID 33806057, 2021).
respiratory disease (1 paper, 2024). "Some of the identified candidate genes, such as G Protein-Coupled Receptor Kinase 7 (GRK7), ADAM metallopeptidase domain 9 (ADAM9), furin, paired basic amino acid cleaving enzyme (FURIN), and Integrin Subunit Alpha V (ITGAV) were previously associated with bovine respiratory disease susceptibility." (PMID 38892353, 2024).